BEST1 (bestrophin 1)
Diseases named in the same sentence as BEST1 in open-access papers (continued):
Sharing a sentence is not in itself a finding about the gene and the disease.
autosomal recessive bestrophinopathy (continued). "A distinct retinal disorder, named autosomal recessive bestrophinopathy (ARB), has recently been described in association with biallelic BEST1 mutations." (PMID 22162627, 2011). "Genetic mutations in the bestrophin-1 (BEST1) gene are more commonly associated with hereditary ophthalmic conditions, which have collectively been referred to as bestrophinopathies." (PMID 39742182, 2024). "This autosomal dominant disorder, along with the rest of bestrophinopathies (ARB, ADVIRC, AVMD, and RP50),iscaused by over 350 mutations in BEST1 with variable expression, different modes of inheritance, and cases of incomplete penetrance." (PMID 35806438, 2022). "In contrast to other phenotypes of bestrophinopathies that result from dominant mutations, ARB is associated with recessive biallelic mutations in the BEST1 gene." (PMID 36527004, 2022). "Autosomal recessive bestrophinopathy (ARB) and Best vitelliform macular dystrophy (BVMD) are both associated with mutations in the Bestrophin 1 (BEST1) gene." (PMID 35295952, 2022). "The clinical manifestations of bestrophinopathies and the role of Best1 in these diseases are reviewed elsewhere." (PMID 34612806, 2021). "Genetic mutation of the human BEST1 gene, which encodes a Ca2+-activated Cl- channel (BEST1) predominantly expressed in retinal pigment epithelium (RPE), causes a spectrum of retinal degenerative disorders commonly known as bestrophinopathies." (PMID 34061021, 2021). "Six patients (12 eyes) had bestrophinopathy, including 4 patients diagnosed as autosomal recessive bestrophinopathy (ARB) with homozygous or compound heterozygous mutations in BEST1 gene and 2 patients diagnosed as Best disease with heterozygous mutations in BEST1 gene." (PMID 33876278, 2021). "The successful restoration of bestrophin 1 function in patient-derived RPE confirms 4PBA as a promising therapeutic treatment for bestrophinopathies and validates the data from cell models used in compound screening." (PMID 32421148, 2020). "This BEST1- Cl− current- LP correlation suggests gene supplementation as a promising approach for curing bestrophinopathies." (PMID 31836750, 2019). "Bestrophin-1 (BEST1) gene is associated with a wide range of ocular phenotypes, collectively termed as Bestrophinopathy." (PMID 31766397, 2019). "Such variable phenotypes of bestrophinopathy result from variable expression patterns and reduced penetrance of BEST1." (PMID 28831140, 2017). "We found the same dialysis activated Cl- currents in bone marrow derived neutrophils from CLIC1, CLCN3, CLCN7 and KCC3 KO animals and in blood neutrophils from a Bestrophinopathy patient (Best1 H178P) (representative current traces)." (PMID 28553230, 2017). "Autosomal recessive bestrophinopathy (ARB), first described in detail in 2008, is another member of the phenotypic spectrum associated with mutations in the BEST1 gene." (PMID 27071392, 2016). "Taking into account the considerably variable expressivity of BEST1-associated phenotypes and the fact that only a small percentage of BEST1 mutations have been carefully studied, other unrecognized molecular mechanisms might contribute to the bestrophinopathy phenotypic spectrum." (PMID 24143172, 2013). "Our study on rAAV-mediated BEST1 transgene expression in the canine RPE represents a first step towards gene augmentation therapy for bestrophinopathies." (PMID 24143172, 2013). "As demonstrated in these consanguineous families, a great clinical variability is associated with homozygous mutations in BEST1, ranging from severe dominant BVMD with reduced penetrance in heterozygotes to autosomal recessive bestrophinopathy." (PMID 21738390, 2011). "Autosomal recessive bestrophinopathy (ARB) is a newly defined retinal dystrophy caused by biallelic mutations in bestrophin-1 (BEST1) and is hypothesized to represent the null bestrophin-1 phenotype in humans." (PMID 21203346, 2010).
autosomal recessive bestrophinopathy (continued). "Over 350 mutations in BEST1 have been identified and result in clinically distinct diseases including Best vitelliform macular dystrophy (BVMD), autosomal recessive Bestrophinopathy (ARB), autosomal dominant vitreoretinochoroidopathy (ADVIRC) and retinitis pigmentosa (RP)." (PMID 37110551, 2023). "Finally, the presence of compound heterozygous mutations in the BEST1 gene is conclusive in the final diagnosis due to the diverse phenotypes of ARB and overlapping clinical features of bestrophinopathy spectrum diseases." (PMID 35885980, 2022). "Notably, similar signatures, including retinoschisis, mild peripheral angiographic leakage, and ACG, could also be found in autosomal recessive bestrophinopathy (ARB) caused by mutations in both alleles of the BEST1 gene." (PMID 38983543, 2022). "Therefore, further studies are warranted to connect the functionality of the BEST1 channel to the pathogenesis and progression of bestrophinopathies." (PMID 35885980, 2022). "As there is no effective treatment for bestrophinopathies yet, dissecting the molecular bases of different BEST1 mutations is critical for rational design of therapeutic strategies." (PMID 34061021, 2021). "Best1 is predominantly expressed in the RPE of the human retina, but it is not exactly clear how mutations in BEST1 lead to the molecular pathology of bestrophinopathies." (PMID 34612806, 2021). "4PBA and 2-NOAA can rescue the global and membrane expression of mutant bestrophin 1 associated with autosomal dominant disease (Best vitelliform macular dystrophy [BVMD]) and autosome recessive bestrophinopathy (ARB), and these small molecules have different modes of action." (PMID 32421148, 2020). "Testing the efficacy of 4PBA on additional mutant bestrophin 1 proteins to the seven investigated here is necessary to confirm the putative utility of 4PBA as a therapeutic treatment for bestrophinopathies, as are in vivo studies to show the in vitro action of 4PBA is consistent." (PMID 32421148, 2020). "Lastly, we tested if 4PBA and 2-NOAA could functionally rescue bestrophin 1 function in RPE generated from induced pluripotent stem cells (iPSC-RPEs) derived from patients with a dominant or recessive bestrophinopathy." (PMID 32421148, 2020). "However, ADVIRC is distinct from other bestrophinopathies as the initial dystrophy occurs in the periphery rather than macular area, and is often accompanied by abnormal ocular development, implicating BEST1 in normal eye development." (PMID 27653836, 2016). "Over 250 variants in the bestrophin-1 gene, BEST1, are associated with a group of retinal degenerative diseases collectively known as bestrophinopathies [Best disease, autosomal dominant vitreoretinochoroidopathy, retinitis pigmentosa (RP), autosomal recessive bestrophinopathy (ARB)]." (PMID 27519691, 2016). "Heterozygous mutations in BEST1 may also cause the adult form of VMD, autosomal recessive bestrophinopathies, other autosomal dominant bestrophinopathies, and rare vitreoretinochoroidopathy." (PMID 20057903, 2009). "Compounds were tested for their ability to restore the Cl− conductance of Best1 mutants (p.L234V associated with BVMD and p.M325T associated with ARB) at 100-fold lower concentrations (25 μM) than 4PBA to identify more effective drugs for the treatment of the bestrophinopathies." (PMID 37110551, 2023). "As the BEST1 genomic locus recognized by our BVSi does not have any reported disease-causing mutations or polymorphisms, this BVSi design is universally suited for BEST1 silencing in bestrophinopathy patients no matter where their mutations are located within the gene." (PMID 34061021, 2021). "For instance, the onset of AD vitelliform macular dystrophy (OMIM #153700) associated with mutations in the BEST1 gene may vary from infancy to adulthood, while AD vitreoretinochoroidopathy (OMIM #193220) and AR bestrophinopathy (OMIM #611809) usually manifest in the first decade of life." (PMID 34946832, 2021).
autosomal recessive bestrophinopathy (continued). "Importantly, BEST1 dominant and recessive mutations are both rescuable at a similar efficacy by gene augmentation via adeno-associated virus (AAV), providing a proof-of-concept for curing the vast majority of bestrophinopathies." (PMID 31836750, 2019). "As for autosomal recessive bestrophinopathy (ARB; OMIM611809), Schatz described a patient with yellowish vitelliform lesion identified with biallelic variants of the BEST1 gene in 2006." (PMID 30498755, 2018). "Furthermore, our results suggest that increasing ion channel activity of BEST1 mutants could be a treatment option for bestrophinopathy, including BVMD." (PMID 28831140, 2017). "In regard to the clinical treatment of bestrophinopathies, our study provided an important proof-of-concept for treating ARB caused by BEST1 recessive mutations, as the loss of Ca2+-dependent Cl- current in the ‘null’ BEST1 P274R iPSC-RPE was rescued by viral expression of WT BEST1." (PMID 29063836, 2017). "In order to determine whether the clinically distinct ADVIRC phenotype results from the apical mislocalisation of BEST1, it is also imperative that investigations into BEST1 localisation in other bestrophinopathy-related diseases be repeated in a more reliable polarised RPE cell system." (PMID 27653836, 2016). "In this study, we sought to find more potent drugs for treatment of the bestrophinopathies by virtually screening a library of FDA compounds into a model of the COPII Sec 24a binding site, where 4PBA, a rescuer of mutant Best1 function, has been shown to bind." (PMID 37110551, 2023). "When family history and clinical findings are consistent with AR bestrophinopathy and there are additional pathogenic criteria supporting that the variant might not be clinically neutral, BEST1 variants should be assigned PM2 according to the established AR cutoff (i.e., three homozygotes)." (PMID 34946832, 2021). "Moreover, we demonstrate that gain-of-function mutations are rescuable by a combination of gene augmentation with CRISPR/Cas9-mediated knockdown of endogenous BEST1 expression, providing a universal treatment strategy for all bestrophinopathy patients regardless of their mutation types." (PMID 34061021, 2021). "Bestrophinopathy patient-derived RPE cells exhibit abnormal Ca2+-dependent Cl- currents, underscoring the indispensable role of BEST1 as a CaCC in RPE, although the contribution of other candidate CaCCs cannot be excluded." (PMID 34061021, 2021). "The restoration of bestrophin 1 function in patient-derived RPE confirms the US Food and Drug Administration–approved drug 4PBA as a promising therapeutic treatment for bestrophinopathies." (PMID 32421148, 2020). "Variants in BEST1 are also responsible for other clinically distinct human diseases: autosomal dominant vitreoretinochoroidopathy (ADVIRC) (OMIM #193220), autosomal recessive bestrophinopathy (ARB) (OMIM #611809) and retinitis pigmentosa (RP) (OMIM #613194)." (PMID 31570112, 2019). "Although clinical presentation of the autosomal recessive form of bestrophinopathy is distinct from the autosomal dominant form, both these conditions are known to arise from BEST1 (VMD2) gene alterations." (PMID 29976937, 2018). "BVMD (BVMD, BEST1, OMIM #607854: autosomal dominant) represents the most common bestrophinopathy." (PMID 38610844, 2024). "However, the endogenous BEST1 mutant to WT molecule ratio in the RPE of bestrophinopathy patients with autosomal dominant mutations is still unknown, due to the lack of a quantitative approach to distinguish BEST1 missense variants from the WT counterpart at the protein level." (PMID 34061021, 2021). "While there is currently no effective therapy for any of the three bestrophinopathies, first promising results of a BEST1 gene replacement therapy have been reported for a canine model of ARB." (PMID 32111077, 2020).
autosomal recessive bestrophinopathy (continued). "However, it showed larger currents than other BEST1 mutants, p.Trp93Cys, causing autosomal dominant best vitelliform macular dystrophy (BVMD), and p.Ala195Val, causing autosomal recessive bestrophinopathy (ARB)." (PMID 28831140, 2017). "Unlike the other bestrophinopathies caused by autosomal dominant mutations in BEST1, ARB is associated with recessive mutations." (PMID 29063836, 2017). "Autosomal recessive bestrophinopathy (ARB, OMIM 611809) is a BEST1-related dystrophy of autosomal recessive inheritance." (PMID 36835965, 2023). "However, the BEST1 knock-out mice model did not exhibit bestrophinopathy." (PMID 30498755, 2018).
Best vitelliform macular dystrophy (68 papers, 2009 to 2026). Best vitelliform macular dystrophy (BVMD) is a genetic macular dystrophy characterized by loss of central visual acuity, metamorphopsia and a decrease in the Arden ratio secondary to an egg yolk-like lesion located in the foveal or parafoveal region. "Best Disease, or Best vitelliform macular dystrophy, is the most common autosomal dominant macular dystrophy and is characterized by mutations in BEST1, which encodes a calcium gated ion channel in the RPE." (PMID 40710345, 2025). "The first disease reported by BEST1 sequence variants was Best vitelliform macular dystrophy (BVMD), a retinal dystrophy characterized by bilateral involvement of the maculae with yellowish egg yolk-like lesions." (PMID 40414863, 2025). "Aiming to identify the genetic cause of Best disease in the 134 patients recruited to this study, we screened all 11 BEST1 exons and exon–intron boundaries in 56 index cases and identified likely pathogenic mutations in 43 (∼77%) of the families." (PMID 38411968, 2024). "The current study focused on analyzing the spectrum of reported BEST1 mutations and resulting phenotypes, as well as summarizing the genetic and clinical data of diagnosed Israeli patients with Best disease in order to determine the prevalence of the disease." (PMID 38411968, 2024). "BEST1 mutations have been associated with Best vitelliform macular dystrophy, AOFVD, AD vitreoretinochoroidopathy, autosomal recessive bestrophinopathy, and retinitis pigmentosa." (PMID 38983024, 2023). "Best vitelliform macular dystrophy is caused by mutations in the BEST1 gene located on chromosome 11q13, which encodes bestrophin-1, a protein localized to the basolateral surface of the RPE." (PMID 33066661, 2020). "Best disease (BD), also known as vitelliform macular dystrophy, is an inherited disease of the central retina caused by more than 300 pathogenic variants in the BEST1 gene." (PMID 33154968, 2020). "Mutations in BEST1 often result in Best Vitelliform Macular Dystrophy, but the age of onset, mode of inheritance, disease characteristics and prognosis can vary." (PMID 32260251, 2020). "Here we report the results of the characterization of BEST1 variants in an Italian population consisting of 57 probands and 13 families, thus contributing to the molecular epidemiology of Best disease in our country." (PMID 31570112, 2019). "In case 53 (a male), a pathogenic change in BEST1 explains the Best vitelliform macular dystrophy phenotype, however, a truncating variant in RPGR would also be expected to be causative." (PMID 30718709, 2019). "The majority of disease-associated mutations in BEST1 constitute missense mutations and were shown in vitro to lead to a reduction in mutant protein half-life causing Best disease (BD), a rare autosomal dominant macular dystrophy." (PMID 31201163, 2019). "Bestrophin-1 (BEST1) was initially identified via positional cloning of the gene causing the autosomal dominant Best vitelliform macular dystrophy, also known as Best disease (BD)." (PMID 31201163, 2019). "BEST1 mutations have been previously shown to cause five clinically distinct retinopathies, including Best vitelliform macular dystrophy, ar bestrophinopathy, adult-onset vitelliform macular dystrophy, ad vitreoretinochoroidopathy, and ad RP16." (PMID 29844330, 2018). "The genetic mutation of BEST1 causes at least five retinal degenerative diseases, notably Best vitelliform macular dystrophy (Best disease)." (PMID 30087350, 2018). "Best vitelliform macular dystrophy (BVMD) is an autosomal dominant syndrome associated with BEST1 mutations." (PMID 29976937, 2018).